GUCA2B (guanylate cyclase activator 2B)
Description:
Endogenous activator of intestinal guanylate cyclase. It stimulates this enzyme through the same receptor binding region as the heat-stable enterotoxins. May be a potent physiological regulator of intestinal fluid and electrolyte transport. May be an autocrine/paracrine regulator of intestinal salt and water transport.
Synonyms: GCAP-II; UGN
Tractability: Antibody: its Gene Ontology location is reachable by antibodies, with high confidence; UniProt places it where antibodies can reach, with medium confidence; UniProt predicts a signal peptide or a membrane-spanning region.
Gene: Protein-coding gene on chromosome 1 (42,153,410 to 42,155,820, forward strand). Ensembl gene ENSG00000044012.
Subcellular location: Secreted
Pathways (Reactome):
Digestion and absorption: Digestion
Gene Ontology:
Molecular function: protein binding; guanylate cyclase activator activity
Biological process: adipose tissue development; cGMP metabolic process; energy homeostasis; glucose homeostasis; multicellular organism growth; reduction of food intake in response to dietary excess; response to glucose
Cellular component: extracellular exosome; extracellular region
Genetic constraint (gnomAD): Loss-of-function variants: 6 observed, 11.42 expected, observed/expected ratio (o/e) 0.53, 90% interval 0.29 to 1.04. The upper end of that interval is the gene's LOEUF score, 1.04, which puts it in group 4 of 6, group 1 being the genes least tolerant of losing a copy. Missense variants: 129 observed, 138.08 expected, observed/expected ratio (o/e) 0.93, 90% interval 0.81 to 1.08. Synonymous variants: 66 observed, 64.53 expected, observed/expected ratio (o/e) 1.02, 90% interval 0.84 to 1.25.
Homologues: Orthologues: chimpanzee GUCA2B (98% identical), macaque GUCA2B (96% identical), pig GUCA2B (79% identical), guinea pig GUCA2B (70% identical), mouse Guca2b (63% identical), rat Guca2b (62% identical), dog GUCA2B (58% identical). Paralogues in human: GUCA2A (33% identical).
Diseases named in the same sentence as GUCA2B in open-access papers:
GUCA2B is named in the same sentence as 15 diseases in open-access papers, as found by Europe PMC text mining. Sharing a sentence is not in itself a finding about the gene and the disease. The quoted sentences say what the papers report.
Obesity (6 papers, 2016 to 2025). Accumulation of substantial excess body fat. "A decrease in GUCA2A mRNA and protein expression (both P<0.05) was found in the pancreas of rats with diet-induced obesity, whereas GUCA2B and GUCY2C gene and protein differences fell out of statistical significance." (PMID 37274331, 2023). "Intestinal and circulating GUCA2B are decreased in experimental and human obesity, resulting in an impaired uroguanylin-GUCY2C endocrine axis in the obese state." (PMID 37274331, 2023). "Additionally, a recent report on the gastrointestinal peptides proguanylin (GUCA2A) and prouroguanylin (GUCA2B), which play major roles in obesity and satiety, demonstrated a protective effect against lipotoxicity and mitochondrial dysfunction." (PMID 39524892, 2024). "Thus, GUCA2B/Guca2b-expressing cells in the small intestine probably have sensory properties and might be of importance in the pathogenesis of obesity." (PMID 27044258, 2016). "An upregulation of GUCA2A and GUCY2C, but not GUCA2B, was observed in pancreata from rats with diet-induced obesity one month after sleeve gastrectomy." (PMID 37274331, 2023).
colorectal cancer (5 papers, 2011 to 2023). A primary or metastatic malignant neoplasm that affects the colon or rectum. "Guanylate cyclase activator 2B, which is involved in the excretion pathway, and it has been reported to predict and assess the survival of colorectal cancer patients." (PMID 36718454, 2023).
Hypertension (3 papers, 2014 to 2022). The presence of chronic increased pressure in the systemic arterial system. "However, more research is needed to identify and characterize susceptibility mutations in the GUCA2B gene for essential hypertension." (PMID 35846281, 2022). "In the RNA-Seq dataset, the identification of four DEGs related to regulation of BP, namely Guca2b, Hmox1, Hba2, and Hba-a2, is of particular interest for elucidating possible mechanisms by which l-NAME and/or l-citrulline medicates programmed hypertension." (PMID 25517031, 2014).
adenoma (2 papers, 2012 to 2015). A neoplasm arising from the epithelium. "GUCA2B, a gene coding for uroguanylin, has been found to be down regulated by 8-fold in adenoma." (PMID 26356760, 2015). "GUCA2B (uroguanylin) is an endogenous activator of the guanylate cyclase-2C receptor found to be down regulated 8-fold in adenoma, and its expression is detected in blood and urine.Therefore, GUCA2B could be regarded as a non-invasive biomarker for the early detection of CRC." (PMID 22496748, 2012).
colon cancer (2 papers, 2017 to 2020). "As an example, IG-SVM achieved a classification accuracy of 90.32% for colon cancer, which is difficult to be accurately classified, only based on three genes including CSRP1, MYL9, and GUCA2B." (PMID 29246519, 2017).
inflammatory bowel disease (2 papers, 2016 to 2019). A spectrum of small and large bowel inflammatory diseases of unknown etiology. "GUCA2A, GUCA2B, and GUCY2C are downregulated in inflammatory bowel disease, which may have implications in inflammatory bowel disease pathogenesis." (PMID 31467713, 2019). "Recently, we reported that GUCA2A, GUCA2B and GUCY2C, plus several steps of the GC-C signaling pathway, are down-regulated in inflammatory bowel disease (IBD)." (PMID 27044258, 2016).
ulcerative colitis (1 paper, 2021). An inflammatory bowel disease involving the mucosal surface of the large intestine and rectum. "In long- and short duration ulcerative colitis, GUCA2B displays a differential expression in parallel with B4GALNT2." (PMID 33919332, 2021).
tumor (7 papers, 2011 to 2023). "The vascular cell adhesion protein 1, basement membrane-specific heparan sulfate proteoglycan core protein, resistin-like alpha, guanylate cyclase activator 2B, and lymphocyte antigen 6C1 protein in the urine of the tumor-resected group decreased, while the alpha-amylase 1 protein increased." (PMID 36718454, 2023). "Consistent with the expression of GUCA2A in our study, the expression of GUCA2B was significantly downregulated in CRC tissues and had a relative high weight in the red module, which further indicates that GUCA2A and GUCA2B may play a consistent role in CRC neoplasia." (PMID 31467713, 2019). "Gelatinase activity was one major GO annotation of these eight genes (CA7, SPIB, GUCA2B, AQP8, IL6R, SPP1, TCN1, and CWH4) and is related to tumor progress and metastasis." (PMID 24959000, 2014). "The most notable examples of down-regulated genes were GUCA2B (FC = 187), TMIGD1 (FC = 129) and CA1 (FC = 121), while CST1 and S100A2 (FC = 131/88.7, respectively) were highly expressed in tumours but not in normal tissue." (PMID 30231850, 2018).
cancer (3 papers, 2021 to 2023). A tumor composed of atypical neoplastic, often pleomorphic cells that invade other tissues. "C1-2 cells lacked reported cancer cell functional alterations, suggesting that they are enriched in normal epithelial cells, and C1 cells expressed markers of mature colonocytes (GUCA2B, SLC26A3 and CA1)." (PMID 36209225, 2022).
GUCA2B also shares sentences with these, for which no sentence is quoted: acute coronary syndrome (1 paper); diabetes (1); essential hypertension (1); familial partial lipodystrophy (1); irritable bowel syndrome (1); prion disease (1).